SPARC (secreted protein acidic and cysteine rich)
Diseases named in the same sentence as SPARC in open-access papers (continued):
Sharing a sentence is not in itself a finding about the gene and the disease.
tumor (continued). "In tumor tissues, we found SPARC promoter hypermethylation in the 58% of NSCLCs analyzed; in particular, it was detected in 68% of SqCCs and 53% of ADCs." (PMID 32580473, 2020). "The Pt NPs were observed to co-localize with SPARC in tumor cells, which was also confirmed in DNR-resistant tumors." (PMID 31992692, 2020). "TGFβ was also shown to stimulate SPARC function as an essential factor in tumor cell migration where it participates as one of the regulators of the fibronectin network assembly." (PMID 33322258, 2020). "PDAC is a stromal-rich tumour expressing high amounts of secreted protein acidic and rich in cysteine (SPARC)." (PMID 32350413, 2020). "It has been suggested that secreted protein acidic and rich in cysteine (SPARC), one of the myokines that is secreted into the bloodstream by muscle contraction, has tumor-suppressive effects." (PMID 32512862, 2020). "In in vivo targeting experiments, an increase of SPARC-targeted nanoparticles was observed in tumor tissue as compared with the control group." (PMID 33050185, 2020). "Accordingly, as the expression of SPARC was downregulated in HuH-7 cells, the observed tumor size was remarkably smaller compared with the SCR group." (PMID 32670867, 2020). "Univariate analysis showed that OS was significantly correlated with GCAF-derived SPARC expression, tumour invasion, lymph node metastasis, and cancer embolus." (PMID 31139014, 2019). "We present evidence for the first time that the tumour-suppressor role of SPARC in OvCa is mediated through inhibition of OvCa cells–adipocytes interactions, the phenotypic plasticity of omental adipocytes, and metabolic programming." (PMID 30765860, 2019). "Recent work has highlighted stabilin-1 upregulaton in TAMs in a range of cancers, and in an in vivo model of breast cancer the uptake of SPARC, a tumour inhibiting factor, by stabilin-1 on TAMs promoted tumor progression." (PMID 31315308, 2019). "Gender, age, tumor stage, chemotherapy, location and SPARC expression were assessed using univariate Cox regression analysis to identify their impact on DFS." (PMID 31554208, 2019). "A non-autonomous effect exerted by FNhigh DTCs on bone marrow-derived cells (BMDCs) has been ascribed to DTC-secreted SPARC that drives expression of BMP7 in BMDCs to maintain tumor dormancy by inducing senescence in micrometastatic cancer cells." (PMID 31861892, 2019). "Compared with the normal epithelium, the mRNA and protein expression levels of SPARC were found to be substantially higher in tumor tissues." (PMID 31950035, 2019). "Immunofluorescence micrograph demonstrated that the FITC-labeled nanoparticles colocalized with SPARC in tumor (lower row), supporting the tumor targeting effect of BPBBT NPs through the albumin-SPARC binding." (PMID 31101816, 2019). "Our analysis of the clinical data is in line with the results from the cell line co-culture models demonstrating increased tumor cell aggressiveness in the presence of SPARC." (PMID 31554208, 2019). "FNR648-HSA was observed not only in the blood vessel regions but also in the regions distant from vessels and its distribution pattern in the regions away from vessels correlated with SPARC expression in U87MG tumor." (PMID 31695779, 2019). "Of note, the tumor sensitivity to Abraxane® was positively correlated with the overexpression of SPARC." (PMID 31195727, 2019). "Secreted protein acidic and rich in cysteine (SPARC) induced by TAMs as a matricellular protein increases tumor extracellular matrix deposition and interaction and thus promotes tumor cell migration." (PMID 31629410, 2019). "Of the 99 patients of the Vienna cohort, all expressed SPARC in the tumor stroma, but only 16 contained SPARC-positive cancer cells." (PMID 31554208, 2019). "Our earlier studies highlighted the tumour-suppressor effect of secreted protein acidic and rich in cysteine (SPARC) in OvCa through multi-faceted roles inhibiting cancer cell interactions within the peritoneal milieu." (PMID 30765860, 2019).
tumor (continued). "This approach first confirmed the direct autocrine and paracrine effects of SPARC on tumour cell–adipocyte interactions." (PMID 30765860, 2019). "Although still debated, SPARC appeared a crucial driver of tumor angiogenesis, cell proliferation and migration." (PMID 31390840, 2019). "According to the earlier studies, SPARC favors fibronectin and vitronectin interaction with tumor cells through integrins, generating a traction force along ECM fibers." (PMID 31300030, 2019). "To further determine the effect of adipocyte-SPARC on the expression of cytokines in both tumours cells and adipocytes, we determined the mRNA expression of cytokines and chemokines in ID8 and SP–/– and SP+/+ adipocytes in mono- and co-cultures." (PMID 30765860, 2019). "Using RT-PCR and immunofluorescence (IF, for the M-MDSC subset) analyses we show that SPARC is expressed by both PMN- and M-MDSC dependently on concomitant tumor expression of SPARC, being associate to N3DSP and SN25ASP, but not to N3D and SN25A tumors." (PMID 31281314, 2019). "Stabilin-1 was found to play a tumor promoting role in the TS/A model likely through enhanced clearance of SPARC." (PMID 31783695, 2019). "Due to the low number of patients we cannot draw any conclusions about tumor cell-derived SPARC and focused our study on stromal SPARC." (PMID 31554208, 2019). "Nab-PTX has been proven to be 33% more effective than conventional PTX in MX-1 tumor xenografts due to its interaction with SPARC that is over-expressed especially in BC." (PMID 31783552, 2019). "As SPARC has been described as a modulator of cell-matrix interactions, tumor cells were plated on culture substrates consisting of type I collagen with or without rSPARC." (PMID 31554208, 2019). "The matricellular factor SPARC plays different roles in extracellular processes, and its function is strictly related to the cancer model and/or the metastatic grade of the tumour." (PMID 31652569, 2019). "SPARC depletion reduces tumor dissemination that significantly prolongs survival and improves response to cytostatic therapy." (PMID 31062076, 2019). "Specifically, we have shown that SPARC deposited in the tumor stroma is an essential factor in tumor cell migration and invasion." (PMID 31554208, 2019). "In this cohort, SPARC expression in tumour cells negatively correlated with the nuclear expression of the three TFs." (PMID 30765860, 2019). "In U87MG tumor tissue expressing SPARC, the HSA distribution was similar to but also apparently different from that of FITC-dextran." (PMID 31695779, 2019). "The aspect of SPARC as tumor growth is seem to condition dependent, because SPARC also increase cell survival under serum-withdrawal condition 43 or chemotherapy treatment." (PMID 31695779, 2019). "Overall, nab-paclitaxel was thought to target stromal SPARC to incite an antidesmoplastic response to effectively deliver gemcitabine to the tumor site." (PMID 29623263, 2018). "In our model the SCD5-associated spreading reduction correlates with the diminished secretion in the tumor microenvironment of SPARC that is known to modify the extracellular matrix." (PMID 29484133, 2018). "In this study, we found a marked increase in methylation at the promoter of SPARC in the SAM-treated xenograft tumor DNA as compared to controls, suggesting promoter methylation effect of SAM on this promoter as well." (PMID 29435170, 2018). "Tumor DNA from experimental animals treated with SAM showed increased methylation of SPARC by pyrosequencing as compared to vehicle-treated control tumors." (PMID 29435170, 2018). "Immunohistochemistry for α-smooth muscle actin (α-SMA), collagen and SPARC provided clear evidence that desmoplasia, in particular fibroblast density, was reduced in liver metastases compared with matched primary tumours." (PMID 28077438, 2018).
tumor (continued). "We postulated that the T12/Man-BSA NPs was recruited and bound to the tumor spheroids by the overexpression of TfRs and SPARC, and the dual-receptor synergistic effect (SPARC and TfRs) promoting the diffusion into the spheroids." (PMID 29732051, 2018). "SPARC was expressed in tumor cells in ten of the 53 patients (18.9%) evaluated for SPARC and in stromal cells in 47 of the 53 (88.7%) patients." (PMID 28050738, 2017). "In our specimens SPARC staining was strongest in individual cells in the tumor-microenvironment that represented about 10% of the cells in the tumor stroma." (PMID 29176937, 2017). "In the GeparTrio trial, investigators found that high expression of SPARC in tumor cells was significantly correlated with increased pCR rate to neoadjuvant chemotherapy." (PMID 28061451, 2017). "SPARC positive staining was localized in the cytoplasm of tumor stromal cells with either moderate or strong staining." (PMID 29156791, 2017). "Previous studies have suggested that the enhanced tumor uptake of NPTX is mediated by the binding of albumin to SPARC expressed on stromal cells." (PMID 29172757, 2017). "Double-immunofluorescence staining was used to reveal the cellular source of SPARC in tumor tissues." (PMID 29156791, 2017). "Correspondingly, SPARC expression in tumor cells correlated with EMT features, and the expansion and infiltration of myeloid-derived suppressor cells, which contribute to tumor growth and dissemination, was indirectly regulated by SPARC, as well as OPN." (PMID 29065446, 2017). "In our dataset evidence of inflammation comes from the increased levels of THBS2 and SPARC in the tumor stroma that are both induced by IL1β in fibroblasts in vitro." (PMID 29176937, 2017). "SPARC is beneficial to the growth of tumor and the interaction between tumor and stroma, which is contributing to malignant invasion of tumor." (PMID 29262657, 2017). "A protein secreted by the tumor, secreted protein acidic and rich in cysteine (SPARC) is postulated to bind and entrap the albumin, allowing release of the hydrophobic drug to the tumor cell membrane." (PMID 28881739, 2017). "In the clinical samples, the expression of SPARC in tumor tissues is higher than that in normal tissues and the highest SPARC expression was detected in grade IV tumors." (PMID 28718842, 2017). "Previous research based on immunohistochemical staining and morphological evaluation assumed that tumor stromal fibroblasts were important source of stroma-based SPARC." (PMID 29156791, 2017). "In a murine tumor model, SPARC treatment significantly induced phosphorylation of Akt and WNK1 in lung tumor nodules when compared to control mice." (PMID 28969021, 2017). "The expression of interstitial SPARC is often characterized by a wide range of tumor necrosis, acidity, hypoxia and oxidative stress, which are the main features of an aggressive tumor." (PMID 29262657, 2017). "SPARC derived from either tumor cells or tumor stromal cells plays various roles in tumor progression." (PMID 29156791, 2017). "The SPARC expression in grade IV tumor samples is higher when compared to that in grade I–III tumor samples." (PMID 28718842, 2017). "Immunohistochemistry (IHC) study was performed on type I EC tumor samples using five adipokines (SPARC, RBP4 (Retinol Binding Protein 4), adiponectin, TNF α, IL-6) and hormonal receptors (estrogen receptor and progesterone receptor)." (PMID 28505082, 2017). "SPARC plays a role in tumor invasion and metastasis via modulation of cell–cell and cell–matrix interactions." (PMID 28425924, 2017). "As the invasion of the tumor from the mucosa to the serosa, higher positivity of SPARC was observed in the tumor tissue." (PMID 29156791, 2017). "SPARC participates in tumor angiogenesis, migration, proliferation and survival through affecting growth factor signaling and cell-ECM interactions." (PMID 29156791, 2017).
tumor (continued). "Understanding the role of signaling pathways involved in surviving and inducing cell death with SPARC expression is important for the development of more effective tumor therapies including SPARC gene therapy alone or in combination with other drugs." (PMID 28435518, 2017). "In four of seven tumor pairs, SPARC expression in tumor region is higher than that in adjacent normal region." (PMID 28718842, 2017). "Patients were identified as high SPARC expressers if at least 50 % of the tumor cells displayed 2+ staining (56 %)." (PMID 27544129, 2016). "The level of SPARC mRNA was also determined on total RNA prepared from the tumor transplants generated by the TIC from the SPARC-transfected As+3-and Cd+2-transformed cell lines (TIC tumor transplants)." (PMID 26783756, 2016). "More studies are needed to explore the exact mechanism by which SPARC regulates tumor development and progression." (PMID 27421134, 2016). "The exact role that SPARC plays in the development and progression of cancer is still under investigation since SPARC has been classified as both a tumor suppressor and oncogene depending on the cancer under study." (PMID 26783756, 2016). "Tumor initiating cells isolated from SPARC-transfected As+3-and Cd+2-transformed cell lines have an inherent mechanism to suppress the expression of SPARC mRNA." (PMID 26783756, 2016). "We have further demonstrated the expression of endogenous SPARC in TS/A cells cultured in vitro using Western blotting and in TS/A tumor tissues using immunofluorescent staining and confocal microscopy." (PMID 27105498, 2016). "SPARC exerts an autocrine and a paracrine inhibition of tumor cell proliferation evident in cell cycle arrest at G1/S phase." (PMID 27564266, 2016). "Since SPARC was reported to directly inhibit tumor cell proliferation and induce tumor cell apoptosis we tested both of these effects of recombinant SPARC on TS/A cells in vitro." (PMID 27105498, 2016). "SPARC has also been shown to function as a tumor suppressor in other types of cancer, although its role in tumor pathogenesis appears to be context and cell-type dependent." (PMID 27776337, 2016). "As expected, we found that tumors with high-levels of stroma-derived SPARC exhibited decreased tumor growth and inhibited angiogenesis." (PMID 27776337, 2016). "The growth of the SPARC-transfected and vector control tumor transplants in the immune compromised mice were similar to each another (data not shown) and to that previously published for the original non-transfected transformed cell lines." (PMID 26783756, 2016). "ABCG2, Cul3, IGFBPR5, PTEN, and SPARC genes levels of expression were related to the malignant phenotype in tumor cells, and those differential expressions were found to be modulated by Maitake in our previous studies." (PMID 27401257, 2016). "The only tumor transplant having a level of SPARC mRNA expression convincingly above background was the As#6 cell line transfected with SPARC." (PMID 26783756, 2016). "Our results suggest stabilin-1 mediated silent clearance of extracellular tumor growth-inhibiting factors (e.g. SPARC) as a mechanism of stabilin-1 induced tumor growth." (PMID 27105498, 2016). "By enhancing the transport of albumin from the vascular space to tumors, SPARC mediates lipid deposition in tumor tissue, leading to lipotoxicity." (PMID 27776337, 2016). "Overall, we suggest that modulation of tumor growth by stabilin-1 is mediated through dynamic removal of SPARC and presumably other unidentified tumor-regulating factors from extracellular space." (PMID 27105498, 2016). "Overall, our data indicate that stabilin-1 is involved in the clearance and sequestration of tumor growth modulating factors such as SPARC from extracellular space." (PMID 27105498, 2016). "Significant accumulation of lipids in the presence of SPARC was also present in other xenografted tumor models, while low amounts of lipids were detected in the SPARC-negative tumors." (PMID 27776337, 2016).
tumor (continued). "In contrast, the tumor xenografts with high levels of stroma-derived SPARC contained fewer red blood cells and more stromal tissue." (PMID 27776337, 2016). "One possible explanation for the finding that SPARC expression was suppressed in the tumor transplants from the SPARC-transfected As+3-and Cd+2-transformed cell lines is that the TICs responsible for tumor formation did not express SPARC." (PMID 26783756, 2016). "SPARC protein was found predominantly in the cytoplasm of tumor cells, and 52.1% cases showed high cytoplasmic staining." (PMID 27421134, 2016). "In a recent article, tumor-derived SPARC was found to trigger endothelial paracellular permeability in primary human umbilical vein endothelial cell (HUVEC) monolayers via VCAM1 and p38 signaling, thus disrupting endothelial monolayer integrity." (PMID 27581191, 2016). "To investigate if SPARC mediated the lipid deposition by chaperoning albumin-bound FA from the intravascular space to the tumor tissue, we tested the binding affinity of SPARC to albumin using pull-down assays and SPR analysis." (PMID 27776337, 2016). "For example, in ovarian and colorectal cancer as well as neuroblastoma, SPARC has demonstrated antitumorigenic properties inhibiting angiogenesis and functioning as a tumor suppressor." (PMID 27544129, 2016). "This is especially true for the SPARC protein since as detailed in the introduction it has been found to have contrasting properties and has been proposed to be a tumor suppressor or an oncogene depending on the tumor." (PMID 26783756, 2016). "In conclusion, although the mechanisms by which SPARC regulates tumor growth are complex, we show the importance of the biological role of SPARC as a chaperone for serum albumin." (PMID 27776337, 2016). "In contrast, the As#3 cell line transfected with the SPARC open reading frame demonstrated multiple areas of focal expression of the SPARC protein representative of approximately 10% of the overall tumor mass." (PMID 26783756, 2016). "Using primary biopsy and resection specimens, SPARC expression was evaluated in terms of patient and tumor characteristics, treatment, and outcome including OS and time to recurrent disease." (PMID 27544129, 2016). "The ability of SPARC to modulate cell-cell and cell-matrix interactions and to have de-adhesive properties has led to many studies assessing its role in tumor cell growth, differentiation, metastasis, and invasion." (PMID 26783756, 2016). "In this study we have demonstrated that stabilin-1 endocytic ligand SPARC was indeed involved in induction of tumor cell death although its effect was moderate." (PMID 27105498, 2016). "Comparable levels of SPARC expression were detected in wt and stabilin-1 ko tumors suggesting involvement of SPARC in the regulation of TS/A tumor growth in both mouse strains." (PMID 27105498, 2016). "The ability of the SPARC-transfected urospheres to generate a subcutaneous tumor in immune compromised mice allows them to be defined as a population of TIC." (PMID 26783756, 2016). "Serum protein acidic and rich in cysteine (SPARC), also known as osteonectin and BM-40, is a matricellular glycoprotein that is secreted by tumor and/or surrounding stroma." (PMID 27544129, 2016). "Human microvascular blood vessels express elevated levels of SPARC at sites of injury, infection, and neoplasia relative to healthy tissue." (PMID 27581191, 2016). "Although SPARC controls important mechanisms in tumor development and progression, its actual function is still contradictory and not fully understood." (PMID 27421134, 2016). "High immunostaining of SPARC significantly correlated with tumor differentiation (P = 0.004), and independently predicted shorter overall survival (OS) (HR = 1.446, P = 0.022), based on the current IHC evaluation." (PMID 28053291, 2016).